IL6 (interleukin 6)
Diseases named in the same sentence as IL6 in open-access papers (continued):
Sharing a sentence is not in itself a finding about the gene and the disease.
Insulin resistance (continued). "Excessive lipid accumulation was reported to induce insulin resistance in adipocytes, hepatocytes, and skeletal muscle cells by increasing the levels of various proinflammatory cytokines, including IL-1β, IL-6, TNFα, and MCP1." (PMID 35889886, 2022). "Deletion of JNK1 in adipose tissue reduces IL-6 levels, preventing insulin resistance and hepatic steatosis in a DIO model." (PMID 35112705, 2022). "A combination of counter regulatory hormones (e.g., glucagon and growth hormone) and proinflammatory cytokines such as tumor necrosis factor alpha (TNF-α), interleukin-1 (IL-1), and interleukin-6 (IL6) lead to insulin resistance and hyperglycemia." (PMID 35178208, 2022). "IL6 is an inflammatory factor, which can increase insulin resistance by upregulating the expression of cytokine signal pathway inhibitor 3, while blocking IL6 signal transduction can effectively improve glucose metabolism and insulin sensitivity." (PMID 36452059, 2022). "Hepatic and peripheral insulin resistance, increased lipolysis, relative insulin deficiency, and decreased glucose cellular uptake due to pro-inflammatory molecules such as interleukin 1 (IL-1), interleukin 6 (IL-6), and tumor necrosis factor α (TNF-α), may also contribute." (PMID 35268392, 2022). "Many studies suggest IL-6 role in mediating several mechanisms including insulin resistance, RAAS activation, and TGF-β1 pathway regulation." (PMID 35811945, 2022). "For example, TNF-α, a cytokine that is known to promote cachexia and is produced by macrophages and adipocytes, and IL-6, which has marked catabolic function, are also involved in insulin resistance in type II diabetic patients." (PMID 34980115, 2022). "Excessive chronic IL-6 production promotes the development of insulin resistance and T2D by impairing the phosphorylation of IR and IRS-1 via the upregulation of SOCS-3 (suppressor of cytokine signaling 3), a potential inhibitor of insulin signaling." (PMID 35629988, 2022). "The second goal of this study was to investigate the relationship between miRNAs and inflammatory factors such as TNF-α, IL-6 and insulin resistance to understand the role of miRNAs in the development of T2DM." (PMID 34077450, 2021). "In line with this notion, genetic knockout of IL-6 attenuates cardiac insulin resistance and inflammation in obese mice." (PMID 34671656, 2021). "There is also evidence to suggest that IL-6 is capable of activating the hypothalamic–pituitary–adrenal axis and accelerating insulin resistance." (PMID 34861824, 2021). "Adipocytokines chemerin, AFABP (adipocyte-specific fatty acid-binding protein), interleukin-4 (IL-4), and interleukin-6 (IL-6) are enlisted in the regulation of insulin resistance and inflammation." (PMID 34007846, 2021). "A study found that increased serum CRP and IL-6 levels correlated with elevated insulin levels and higher insulin resistance index (HOMA-IR) scores, further suggesting that inflammatory factors are closely related to IR." (PMID 33714202, 2021). "The increased macrophages secrete numerous cytokines and chemokines, such as TNF-α, IL-1, and IL-6, and these cytokines lead to insulin resistance." (PMID 34867288, 2021). "The other important myokine is interleukin 6 (IL-6), which plays a potential role in regulating fatty acid oxidation in the liver and insulin resistance." (PMID 33557355, 2021). "Based on experimental studies, up-regulation of TNF-α and IL-6 induces insulin resistance through activation of JNK and MAPK signaling pathways and consequently disrupts insulin signaling pathway leading to insulin resistance." (PMID 34077450, 2021). "This induces the expression of inflammatory cytokines such as tumor necrosis factor α (TNF-α) and interleukin 6 (IL-6), contributing to inflammation and insulin resistance, which can increase fat accumulation in the liver." (PMID 34441497, 2021).
Insulin resistance (continued). "PTSD is associated with low-density lipoprotein-cholesterol, cortisol, interleukin (IL)-2, IL-6, IL-8, leptin, insulin resistance, and tumor necrosis factor (TNF)-α9–12." (PMID 33674663, 2021). "The cytokines involved in the pathogenesis of RA, in particular TNFα, IL-1 and IL-6, also promote the development of insulin resistance." (PMID 33995414, 2021). "IL-6 also affects insulin resistance and mitochondrial activity, and exerts a significant role in vascular diseases, the neuroendocrine system and neuropsychological behavior." (PMID 34680892, 2021). "Skeletal muscle insulin resistance has been shown to be unrelated to long term IL-6 stimulation and further studies are necessary in this area." (PMID 33997590, 2021). "For example, patients with Rheumatoid Arthritis (RA) and Systemic Lupus Erythematosus (SLE) show an increased insulin resistance (IR), which is linked to the systemic inflammation induced by certain inflammatory cytokines (TNF-α and IL-6)." (PMID 34372196, 2021). "Insulin resistance (IR) and diabetes have also been associated with the activation of inflammatory mediators like C-reactive protein (CRP), IL-1β, TNF-α and IL-6 in blood and adipose tissue." (PMID 34026558, 2021). "Animal data suggest that IL-6 mediates hepatic insulin resistance via SOCS3, which blocks autophosphorylation of the insulin receptor." (PMID 34747368, 2021). "Decreased adiponectin and insulin resistance correlate with an increased release of other cytokines and adipokines, including TNFα and IL-6." (PMID 33799622, 2021). "Multiple studies have suggested that IL-6 leads to insulin resistance and promotes muscle atrophy, as skeletal muscle is the main tissue in which insulin stimulates glucose uptake." (PMID 34863141, 2021). "Such alterations in the adipose tissue lead to adipocyte hypertrophy, immune cell infiltration, and increased cytokine (IL-1β, IL-6, TNFα) and chemokine production, which eventually lead to insulin resistance, T2DM, dyslipidemia, and hypertension." (PMID 34299302, 2021). "Recent findings have suggested that IL-6 gene expression is mildly elevated in individuals with insulin resistance." (PMID 34579020, 2021). "It has been indicated that inflammatory mediators such as TNF-α and IL-6 are increased with insulin resistance and play an important role in deregulating glucose homeostasis in type 2 DM." (PMID 33968046, 2021). "It has been shown that ablation of JNK1 in adipose tissue decreases IL6 expression and protects against liver insulin resistance induced by high caloric diet in mice." (PMID 35111744, 2021). "IL-6/Jak2 signaling adversely interferes with the action of insulin, resulting in glucose intolerance and insulin resistance." (PMID 34943061, 2021). "Like TNF-α, IL-6 also promotes insulin resistance by attenuating the expression of IRS-1 and GLUT-4 and deregulating fatty acid metabolism in adipocytes." (PMID 33917607, 2021). "Several studies have reported that IL‐6 is a pro‐inflammatory cytokine that is detected in higher amounts in obese individuals and contributes to the occurrence of type 2 diabetes, insulin resistance and CVDs." (PMID 33709536, 2021). "Proinflammatory cytokines (TNF-α and IL-6) are involved in multiple metabolic pathways related to insulin resistance." (PMID 33917607, 2021). "Nutrient excess and high-fat diets are known to recruit neutrophils into tissues, which then cause insulin resistance both by releasing TNF-⍺ and IL-6 and by upregulating cyclooxygenase." (PMID 34099068, 2021). "IL6 also contributes to insulin resistance by inducing TLR4 expression in skeletal muscle via STAT376." (PMID 33820928, 2021). "Another molecular signaling of insulin resistance mediated by IL-6 is related to STAT-3 activation and the consequent activation of the Suppressor of Cytokine signaling (SOCS), which inhibits tyrosine phosphorylation of IRS-1." (PMID 34360849, 2021).
Insulin resistance (continued). "In adipose tissue, adipokines, including monocyte chemoattractant protein-1, tumor necrosis factor-alpha (TNF-α), and interleukin 6 (IL-6), play major roles in inflammation in type 2 diabetes, insulin resistance, cardiovascular diseases, and cancer." (PMID 34812408, 2021). "Injection of adipose tissue-derived small EV (Exo-like) from obese mice induced a pro-inflammatory state in lean mice, enhancing Tumour Necrosis Factor α (TNFα) and Interleukin-6 (IL-6) circulating levels, glucose intolerance, and insulin resistance." (PMID 33477341, 2021). "M1 macrophages induce an inflammatory and insulin resistance state through the inhibition of insulin signaling, indirectly produced by TNF-α, IL-6, and IL-1β, while M2 macrophages protect against insulin resistance by an IL-10-dependent mechanism." (PMID 34944461, 2021). "IL-6 plays a role in T-cell activation, tissue infiltration, and maintenance of memory responses, as well as orchestrates cellular insulin resistance." (PMID 34831450, 2021). "The presence of proinflammatory cytokines, such as IL-6, IL-1, and TNF-α, has been linked to the pathogenesis of insulin resistance and endothelial dysfunction in metabolic syndrome, contributing to the presence of diffuse subclinical inflammation." (PMID 34445526, 2021). "The inflammatory cytokine IL-6 is known to play an essential role in the inflammation of adipose tissue and insulin resistance." (PMID 33799840, 2021). "IL-6 has been previously implicated in NASH, with increased hepatic expression correlating with disease severity and insulin resistance." (PMID 33766130, 2021). "Currently, it is known that cytokines such as TNF-α and IL-6 favor insulin resistance through inhibition of the insulin signaling cascade." (PMID 34360849, 2021). "Impaired glucose metabolism and insulin resistance are associated with low-grade chronic inflammation, and TNF-α and IL-6 are proposed targets, inter-linking inflammation and insulin resistance." (PMID 34073455, 2021). "IL-6 also prevents the induction of insulin resistance and the deterioration of glucose homeostasis." (PMID 34327205, 2021). "Studies also reported that the inhibition of TNFα and IL-6 prevented the development of insulin resistance in obese animals." (PMID 34869524, 2021). "It is possible that IL-6 in combination with other inflammatory markers such as IL-1b, TNF-a, IL-18 and IL-17 links insulin resistance to NMOSD risk." (PMID 33879088, 2021). "The role of IL-6 in DIO is controversial, as some studies suggest that IL-6 exacerbates insulin resistance and others note beneficial effects." (PMID 34093565, 2021). "Obesity is associated with an increase in adipose tissue size and results in the activation of macrophage inflammatory factors including TNFα, IL-6, and MCP-1 (CCL2), which causes insulin resistance." (PMID 34299302, 2021). "High blood levels of leptin play a major role in insulin resistance by inducing the production of IL-6 and TNF-α." (PMID 34069933, 2021). "Tumour necrosis factor alpha (TNF-α) and interleukin-6 (IL-6) are the main inflammatory cytokines increased in insulin resistance and GDM." (PMID 34658643, 2021). "IL-6, a pleiotropic cytokine, can induce a chronic state of low-degree inflammation and insulin resistance, which is also positively related to CRC tumorigenesis." (PMID 33582655, 2021). "Both tumour necrosis factor and interleukin 6 are cytokines, known to be involved in inflammation-induced insulin resistance of adipose tissue." (PMID 33769190, 2021). "IL6 is derived from many cells, including adipocytes, and serum levels of IL6 correlate with insulin resistance; however, adipose tissue-derived IL6 can regulate hepatic insulin resistance through SOCS3 upregulation." (PMID 35154608, 2021). "T2DM increases insulin resistance, and the inflammatory cytokine interleukin-6 (IL-6) increases plasma triglycerides, resulting in dyslipidemia." (PMID 34836432, 2021).
Insulin resistance (continued). "For example, the interleukin-6 (IL-6) family of cytokines, which regulates inflammation and can induce insulin resistance, enhances ATX expression in adipocytes via glycoprotein 130 (gp130) signaling." (PMID 34502491, 2021). "Such macrophages predominantly present the M1 pro-inflammatory phenotype and promote inflammation by releasing tumor necrosis factor alpha (TNF-α) and interleukin 6 (IL-6), thus contributing to insulin resistance." (PMID 34884217, 2021). "Inflammatory cytokines such as tumor necrosis factor-α, interleukin (IL)-1β and IL-6 activate several inflammatory signaling pathways that promote insulin resistance." (PMID 34887771, 2021). "On the other hand, in adipose tissue and liver, IL-6 exerts proinflammatory activities and induces insulin resistance by upregulating suppressor of cytokine signalling 3 (SOCS3), which is a protein that binds to and inhibits insulin receptor." (PMID 33800490, 2021). "The pro-inflammatory cytokine, IL-6, is a plausible mechanistic link between chronic inflammation and glucose intolerance/insulin resistance via the IL6/Jak2/Stat3 axis." (PMID 34943061, 2021). "Studies on obese patients have outlined that insulin resistance and related disorders are characterized by a cytokine imbalance, with high levels of TNFα, IL-6, IL-1β, CRP, and NF-κB." (PMID 33995414, 2021). "The recruitment of macrophages in adipose tissue is associated with increased IL-6 and TNF-α secretion, leading to insulin resistance." (PMID 34356649, 2021). "Two main adipose tissue-derived inflammatory cytokines have been implicated in insulin resistance including TNF-α and IL-6." (PMID 33800490, 2021). "In contrast to sham surgery, RYGB reduced body weight, improved glucose tolerance and insulin resistance, and decreased serum levels of LPS, IL6 and TNFα." (PMID 34290269, 2021). "On the other hand, the role of IL-6 in insulin resistance is less clear with conflicting literature data." (PMID 33800490, 2021). "The expression of visfatin is regulated by several cytokines such as tumoral necrosis factor-alpha (TNF α), interleukin-6 (IL-6), and lipopolysaccharide that are known to promote insulin resistance." (PMID 34300193, 2021). "In fact, the literature has reported that IL-6 concentrations significantly predict both subclinical (sarcopenia and insulin resistance) and clinical (disability and mortality) conditions in older people." (PMID 33815869, 2021). "A high level of endotoxemia has been found to increase the concentrations of tumour necrosis factor α (TNF-α) and interleukin 6 (IL-6) and the promotion of insulin resistance." (PMID 34073366, 2021). "The IKKβ/NF-κB/IL-6 axis was confirmed to be involved in insulin resistance when IL-6 neutralization improved insulin resistance." (PMID 34957242, 2021). "H-Exo vs L-Exo treatment resulted in the induction of an array of inflammatory cytokines detected in the plasma and WAT, including TNF-α and IL-6, which are known to contribute to insulin resistance." (PMID 33431899, 2021). "Level weight gain, visceral fat accumulation, blood lipid, TNF-α, leptin, IL-6 level reduction.Improved insulin resistance (with HOMA-IR)." (PMID 34641407, 2021). "TNF-α and IL-6 are involved in the disruption of insulin signalling and the further stimulation of gene expression related to insulin resistance." (PMID 34658643, 2021). "IL6, combined with cytotoxicity produced by effector cells, leads to the death of pancreatic β-cells and aggravates insulin resistance." (PMID 34746316, 2021). "Biologically speaking, IL‐6 can induce the development of insulin resistance and pathogenesis of T2DM via regulating inflammatory responses." (PMID 33960655, 2021). "AFABP was directly correlated to interleukin-6 (r = 0.50), insulin resistance index (r = 0.26), and body mass index (r = 0.28) and inversely correlated to C-reactive protein (r = −0.27)." (PMID 34007846, 2021).
Insulin resistance (continued). "On the other hand, the virulent strains of H. pylori (cag + with induction of inflammatory factors 71, IL6, CRP) and chronic inflammation affect the insulin-regulating gastroduodenal hormones and ultimately predispose the person to insulin resistance." (PMID 34922625, 2021). "Various studies suggest the involvement of TNF-α, IL-1, and IL-6 in the development of insulin resistance, which is a typical metabolic trait of PCOS." (PMID 33849511, 2021). "Many studies have shown that myokines, such as IL-6, irisin and myostatin, serve as biomarkers for insulin resistance." (PMID 33816504, 2021). "Elevated level of homocysteine leads to insulin resistance by increasing production of interleukin-6 (IL-6), a suppressor of insulin signaling and by inducing endoplasmic reticulum stress, a trigger of insulin resistance." (PMID 32365524, 2020). "Interleukin 6 (IL-6) is a second pro-inflammatory cytokine produced by adipocytes and plays a role in mediating insulin resistance." (PMID 33066473, 2020). "Meanwhile, increased pancreatic IL-1β, IL-6, and IL-8 decrease insulin gene expression in β-pancreatic cells, contributing to increased insulin resistance." (PMID 32903730, 2020). "Low-grade systemic inflammation has been independently implicated in metabolic disorders, such as insulin resistance and T2DM, and is typically presented with elevated levels of pro-inflammatory cytokines (i.e. IL-6, TNF-α, and CRP)." (PMID 33028418, 2020). "During insulin resistance, the production of IL-6 and TNF-α is increased in fat cells and they contribute to intra-abdominal excess fat." (PMID 32120970, 2020). "TNF-α and IL-6 are considered to be contributors to insulin resistance and diabetes mellitus development." (PMID 32015418, 2020). "On the other hand, the activation of A2BR contributes to increased insulin resistance by affecting the production of IL-6 and other cytokines." (PMID 32984382, 2020). "It has been reported that inflammatory markers such as CRP, fibrinogen, and IL-6 increase in insulin resistance." (PMID 32907593, 2020). "Two studies showed that insulin resistance and type 2 diabetes are associated with higher levels of C-reactive protein (CRP), interleukin-6 (IL-6), and tumour necrosis factor-α (TNF- α), which are markers of subclinical systemic inflammation." (PMID 32369922, 2020). "PPARβ/δ is implicated in differentiation, anti-inflammation, fatty acid catabolism, and preventing interleukin-6- (IL-6-) induced insulin resistance." (PMID 33083492, 2020). "Specifically, the proinflammatory cytokine TNF-α has been reported to induce insulin resistance, and previous studies have established the role of inflammatory cytokines IL-1β and IL-6 in the development and progression of T2DM." (PMID 32132984, 2020). "Inflammatory markers, such as the pro-inflammatory cytokines TNF-α and IL-6, are the major contributor to local and systemic insulin resistance." (PMID 31829413, 2020). "It has been reported that interleukin-1β and interleukin-6, which are both involved in insulin resistance, are decreased in individuals with slow eating, indicating the link between eating speed and glycemic parameters observed in the present study." (PMID 32927895, 2020). "The transcription of inflammatory cytokines directly involved in the onset of insulin resistance (Il1β, Il6, and Tnfα) and chemotactic factors for macrophage recruitment (Mcp1) are restored to comparable levels in the cells never exposed to the pollutant." (PMID 33203037, 2020). "What is more, obese adipose tissue contributes to the elevation of inflammatory cytokines, such as tumor necrosis factor α (TNFα) or interleukin-6 (Il-6), leading to chronic inflammation state promoting insulin resistance and cancer development." (PMID 32640537, 2020). "For instance, both TNFα and IL-6 induce insulin resistance in rodents and block insulin action in murine (3T3-L1) adipocytes." (PMID 32397353, 2020).